CCL3 (C-C motif chemokine ligand 3)
Diseases named in the same sentence as CCL3 in open-access papers (continued):
Sharing a sentence is not in itself a finding about the gene and the disease.
infection (continued). "Acute inflammatory chemokines and cytokines, including tumour necrosis factor (TNF)-α, IP-10/CXCK10, MIG/CXCL9, monocyte chemoattractant protein 1 (MCP-1)/CCL2 and macrophage inflammatory protein 1α (MIP-1α)/CCL3, were elevated in the early phase of infection in the lungs of WT mice." (PMID 36243815, 2022). "Finally, a high number of pro-inflammatory cytokines were up-regulated upon infection, such as CXCL10, CCL5, CXCL11, TNF, CCL3, CXCL8, and IL6." (PMID 35893684, 2022). "The increased expression of CCL3 and CCR5 in both PD and non-PD organoids also occurs during infection with respiratory pathogens and is associated with severe manifestations of disease." (PMID 34358063, 2021). "The production of cytokines associated with pregnancy complications (premature birth and infections of the placental/fetal unit) was also increased in L. monocytogenes-infected trophoblasts (CCL2, CCL3, IL-8, CSF2, IL-1α/β, IL-1RA, IL-10, GM-CSF, IL-6, and TNFα)." (PMID 34367171, 2021). "At 3 day post-infection, higher mRNA levels of C-C motif chemokine ligand 2 (CCL2), C-C motif chemokine ligand 3 (CCL3) and C-X-C motif chemokine ligand 10 (CXCL10) were found in the liver of mice infected with the WT strain as compared to mice infected with the ΔspvB strain." (PMID 33475464, 2021). "Similarly, human infection show strong cytokine production, including IL-6, IL-8, IL-12, TNF-α, CSF2, IFN-γ, IL-10, CCL2, CCL3, CCL4, and CCL714–16." (PMID 34615921, 2021). "Furthermore, within the first 48 h of infection, the production of CXCL5, CCL3, CCL5, and, to a lesser extent, GM-CSF, was reduced." (PMID 33670363, 2021). "Furthermore, expression of chemokine genes Ccl3, Cxcl2 and Cxcl10 also significantly increased in migratory ILCs after STM infection." (PMID 33414524, 2021). "At early time points, Fpr2-/- mice showed a significant decrease in CXCL1, CXCL2, IL-1β, CCL2, GM-CSF, IL-6, and CCL3 levels at 1 hour and 3 hours after infection, and an increase in IL-22 and IL-23, but there is no change in TNF-α, as compared with WT mice." (PMID 34899755, 2021). "To further identify whether other chemokines besides KC/GRO were impacted by infection, we also examined the production of CCL2 and CCL3 by ELISA." (PMID 33878120, 2021). "The infection of murine in vitro generated Hoxb8 neutrophils with A. phagocytophilum induced the expression of inducible or type 2 nitric oxide synthase (iNOS or NOS2) mRNA and the secretion of significant amounts of MIP-1α (CCL3), RANTES (CCL5), and TNF." (PMID 33747981, 2021). "In the early stages of the infection, a group of cytokines and pro-inflammatory chemokines are expressed including interleukin-1β (IL-1β), IL-2, IL-6, interleukin-8 (IL-8), both IFN-α/β, tumor necrosis factor (TNFα), CCL, CCL3, CCL5, CCL2, and IP-10." (PMID 34220861, 2021). "The frequencies of single-positive Pfn+ and double-positive IFNγ+ Pfn+ were not modified after infection of ccl3+/+ and, mainly, ccl3−/− mice." (PMID 32194558, 2020). "Thus, the impairment of CXCL1 and CCL3 production in TLR-2KO and TLR-4KO animals affects neutrophil migration to the infection site." (PMID 33193308, 2020). "To identify mechanistic bases for the different numbers of neutrophils at the site of infection, we measured the main chemokine factors for neutrophil attraction, including the CCR1 ligands CCL3, CCL4, and CCL5 and the CXCR2 ligands MIP-2/CXCL-2, KC/CXCL-1, and CXCL5." (PMID 32424099, 2020). "Infection also led to the secretion of the chemokines C-X-C motif ligand 1 (CXCL-1, also known as KC or Gro), monocyte chemoattractant protein 1 (MCP-1), macrophage inflammatory proteins (MIP-1α and MIP-1β, also known as CCL3 and CCL4) by OECs and macrophages." (PMID 33489937, 2020).
infection (continued). "PrimePCR array analysis of hNS/PCs showed that the mRNA levels of inflammatory cytokine related genes (IL-1A, TNFα, IL28A, IL29, NF-KB2), chemokines (CSF2, CCL3, CCL4, CXCR3),TLRs (TLR3, TLR8), IL-10, and Casp9 were all reduced in the Smaducin-6 treated group following ZIKV-FSS13025 infection." (PMID 32544190, 2020). "The chemokine genes (CCL3, CCL4 and CCL5) were also upregulated in these memory-like γδ T cells, which is similar to what had previously been reported to be upregulated in γδ T cells during an active infection." (PMID 33154754, 2020). "Since CD8+ T cells may block HIV/SIV spread from cell- to-cell via CCR5-binding chemokines (i.e., MIP-1a/CCL3, MIP-1b/CCL4, and RANTES/CCL5), we also used viruses which were limited to a single cycle of infection." (PMID 32941545, 2020). "Following infection of the CNS, microglia express markers characteristic of M1 activation including increased expression of Iba-1, as well as chemokines such as C-C motif cytokine 2 (CCL2), CCL3, CCL5, and CCL7." (PMID 32872152, 2020). "According to this, experiments in the A549 cell line (human alveolar type II-like epithelial) with the Long strain of hRSV showed that infection with hRSV induces the secretion of IL-6, CCL3, and CCL5 at 48 h post-infection as compared to non-infected cells." (PMID 30936869, 2019). "The serum levels of CCL3 were elevated at day 1 of postinoculation in Junbo mouse middle ears with no NTHi infection." (PMID 30265765, 2019). "For instance, Th1 cells express high levels of CCR5 but also produce MIP-1α (CCL3), MIP-1β (CCL4) and RANTES (regulated upon activation normal T-cell expressed and secreted) (CCL5), the natural ligands for CCR5, thereby limiting R5 infection in these cultures." (PMID 31487324, 2019). "In the lungs, the levels of proinflammatory cytokines, including interleukin-1β (IL-1β) and granulocyte colony-stimulating factor (G-CSF), and of chemokines, including IP10/CXCL10, MIP1-α/CCL3, MIP1-β/CCL4, MIP2/CXCL2, and KC/CXCL1, were increased and remained high after the infection with WT cells." (PMID 30940711, 2019). "Growth factors and chemokines that support myeloid cell influx and expansion after infection, including M-CSF, G-CSF, MCP-1 (CCL2), MIP-1α (CCL3), MIP-1β (CCL4), KC (CXCL1) and MIP-2 (CXCL2), are also highly abundant in S. aureus infected femurs relative to mock infected femurs." (PMID 30978245, 2019). "In addition, also the extent of gene expression variation was increased at this stage of infection (i.e., up to >8-fold change seen for the inflammatory chemokines CCL2 and CCL3) as compared to the acute phase, where a maximum of 3-fold variation was observed." (PMID 31018522, 2019). "Therefore, using qPCR, we determined the expression of a variety of cytokines with neutrophil chemotactic properties including IL-6, CCL3, CXCL2 and G-CSF, as well as pro-inflammatory cytokines IL-1β and TNF-α at day 3 (105 PFUs) post-infection." (PMID 30787331, 2019). "At lower infection doses, significant differences in height and kinetics of cytokine concentrations in BAL-f were mostly confined to the time point around the maximum cytokine response (2–4 h for IL-1β and Ccl3, 2–8 h for TNF, 8–24 h for Cxcl-1, Ccl2)." (PMID 29734720, 2018). "By nanoString and real-time PCR profiling of the host response to the various mutants, we found that infection with the ΔgliP mutant enhanced expression of multiple chemokines, including CXCL2, CCL3, CCL4, and CCL7, which recruit neutrophils and macrophages to sites of inflammation." (PMID 30052103, 2018). "Regarding the chemokines, diverse studies in humans and mice have indicated that CXCL1, CXCL9, CXCL10, CCL2, CCL3, CCL4, and CCL5 are important in controlling the infection during the acute phase, and the levels of virtually all of them were increased in both BALB/c and C57BL/6 mice." (PMID 29662478, 2018).
infection (continued). "CCR5 is widely expressed on T lymphocytes, macrophages, microglia, and dendritic cells and plays a critical role in inducing migration of immune cells to sites of infection and injury in response to elevated levels of certain C-C-chemokine ligands (MIP-1α/CCL3, MIP-1β/CCL4, CCL5/RANTES)." (PMID 30305110, 2018). "Similar to airway epithelial cells, human macrophages express type I and type III IFNs, IL-1α, IL-1β, IL-6, TNF-α, CXCL8, CCL2 (MCP-1), CCL3 (MIP-1α), CCL4 (MIP1-β), CXCL9, and CXCL10 following infection with seasonal H1N1 or with H5N1, 2009 H1N1 strains demonstrating increased pathogenicity." (PMID 29623073, 2018). "During an infection with another alphaherpesvirus, HSV-1, in mice, it has been reported that CCL3 attracts NK cells, CCL2 recruits monocytes, and CCL5 recruits monocytes, NK cells, and PMNs while CXCL9 recruits T-cells to the sites of infection." (PMID 28241864, 2017). "In our analysis, we observe that a subset of these cytokines reported to be present in the serum also show transcriptional upregulations in PBMCs by 4 days post-infection (IL6, IL1B, IL1RN, CCL8, CXCL10) and by 7 days post-infection (CCL2, CCL3, CSF1, TNF, CXCL1, FAS and CXCL8)." (PMID 27595844, 2016). "The molecules that depicted significant increases in those mAb treated-mice at 96 h after infection were CXCL1 (KC), CCL2 (MCP-1), CCL3 (MIP-1α), CCL4 (MIP-1β), CXCL2 (MIP-2), CXCL5 (LIX), IL-1α, IL-6, G-CSF, M-CSF, and TNF-α (for all, P < 0.01) and IL-1β, IL-15, IL-10, and LIF (for all, P < 0.05)." (PMID 27642235, 2016). "Levels of IL-1β, IL-6, CCL2, CCL3 and CCL5, which are known to play an important role during HSE, were measured in brain homogenates using magnetic bead-based immunoassays prior to (day 0) and on days 6, 8 and 10 following infection." (PMID 27930721, 2016). "As hypothesized, the levels of inflammatory mediators (IL-6, CCL2, CCL3, CXCL1, CXCL10 and IFNα as expected) were lower in the blood and the spleen of Ifnar1-/- mice compared to WT counterparts at all times post-infection, except for IFNγ." (PMID 27792766, 2016). "However, as we demonstrated, CC chemokines CCL3/MIP-1α, CCL4/MIP-1β, and CCL5/RANTES were unable to block infection by T-tropic isolates thus proving the specific and selective inhibition by CXCL12/SDF-1 for this type of viruses." (PMID 26097474, 2015). "Such reagents will allow the critical evaluation of whether and how IDE activity will impact CCL3 and CCL4-mediated immune responses during inflammation and infection and how such effects would impact IDE-based therapy." (PMID 25636406, 2015). "Immune cells, including neutrophils, are recruited to the site of infection by chemokines such as CXCL8 (Interleukin-8) and CCL3 (macrophage inhibitory protein-1alpha-MIP1α) and other inflammatory stimuli including the bacteria-derived N-formyl-methionyl-leucyl-phenylalanine (fMLP)." (PMID 25360483, 2015). "Moreover, L. major amastigotes did not induce the production of the proinflammatory cytokine TNF and the chemokines CCL3 and CCL4, which is in contrast to the higher production during promastigote infection." (PMID 25294956, 2014). "Consistent with the trend of NF-κB activity, the expression levels of three of the four selected chemokines regulated by NF-κB (Ccl2, Ccl3, Ccl5, but not Cxcl1), peaked on day 32 post-infection." (PMID 25116007, 2014). "CCL3/MIP1α not only mediates macrophage chemotaxis, but also significantly enhances differentiation of primed CD8(+) T cells into effector cells and their release into circulation, thus potentiating effective migration to the site of infection." (PMID 25133186, 2014). "Furthermore, our study also showed decreased expression of the chemokines CCL3, CCL4 and CCL5 in the liver and ileum of CCR5-/- mice along with reduced induction of the transcription factors Foxp3, T-bet and GATA-3 after infection." (PMID 25119429, 2014).
infection (continued). "In this context, there is a marked induction of CCL2, CCL3, CCL4, CCL5, CXCL8, and CXCL10 after infection with SIV, as well as a systemic increase of CCL2, CXCL8, and CXCL10 in humans, concurrently with viremia peak after infection with HIV." (PMID 25313360, 2014). "Indeed, when similar infectious doses are applied, although infection with virulent Kp52.145 is lethal, the cytokines IL-1β, IL-6, and IL-17 and the chemokines CCL2, CCL3 and CCL4 are produced in similar manner." (PMID 23554169, 2013). "An increase in mRNA levels for a number of host immunomodulatory genes, including chemokines, CCL3, CCL5 and CXCL2 was observed at 4 h post-infection compared to mock-infected cells and a reduction to similar levels as in mock-infected cells at 16 h post-infection." (PMID 23265239, 2013). "By contrast, at 7 days post infection, the levels of CCL2, CCL3, CXCL2, IFN-γ and the anti-inflammatory cytokine IL-10 were significantly lower in influenza A virus-infected Nox1−/y lung compared to WT control, whereas IL-β, IL-6, TNF-α, and GM-CSF were similar between the two strains of mice." (PMID 23577160, 2013). "UV-inactivated HSV-1 elicited a greater CCL3 and CXCL10 response compared to infection with replication competent virus; therefore, the present data support previous findings suggesting that viral replication products inhibit IFN and chemokine expression in human macrophages as well as other cells." (PMID 23062757, 2012). "HSV-1 DNA released during early infection may be recognized by IFI16, resulting in expression of CCL3; while, CXCL10 expression is mediated via an IFI16-independent pathway." (PMID 23062757, 2012). "Infection with L. tropica led to increased serum levels of chemokines CCL2, CCL3 and CCL5." (PMID 22679519, 2012). "While animals lacking perforin exhibited only a modest increase in susceptibility (∼10 fold) compared to wt memory mice, none of the anti-CCL3-treated groups controlled the challenge infection." (PMID 22241983, 2011). "As expected, primary or memory infected mice treated with anti-CD8 or anti-CCL3 did not control the infection." (PMID 22241983, 2011). "Treatment of mice with anti-CCL3 prior to RSV infection did not significantly alter cell recruitment on day 4 post infection nor the percentage of NK cells recruited." (PMID 20195359, 2010). "MIP-1α/CCL3 concentration in plasma was significantly reduced at three months post treatment, an indication that MIP-1α/CCL3 may be an inflammatory factor produced during S. haematobium infection and is downregulated when the infection is eliminated." (PMID 19852800, 2009). "Note the smaller scales for the cytokines in panels A and B.)Levels tended to normalize to baseline values within 3–4 weeks of infection in all animals, with IL2, IL4, IL12p40, IFNγ, and CCL3 increasing again after 6 weeks of SHIV-RT infection of the naïve animals (not statistically significant)." (PMID 20011586, 2009). "Given our earlier studies on the essential role of CCL3 in eliciting neutrophil recruitment, it is interesting to note that the absence of IFNγ signaling had no impact on local production of this chemokine in response to PVM infection." (PMID 19298652, 2009). "Neutrophil recruitment in response to PVM infection was diminished five-fold in IFNγ receptor gene-deleted mice, although neutrophils from IFNγR -/- mice expressed transcripts for the CCL3 receptor, CCR1 and responded functionally to CCL3 ex vivo." (PMID 19298652, 2009). "Thus, the release CCL3 not only promotes APC infiltration at the site of infection but also promotes the differentiation of CD8+CTLs into effector CD8+CTLs and their migration to the site of infection." (PMID 41009359, 2025). "In contrast, the downregulation of RANTES/CCL5, MIP-1α/CCL3, and MIP-1β/CCL4 from the early to middle phase of the infection as well as the downregulation of MIG/CXCL9, IP-10/CXCL10, and IL-13 in the middle phase of the infection were observed in aged BALB/c mice." (PMID 35264719, 2022).
infection (continued). "As a promiscuous metalloprotease, IDE can degrade a wide range of substrates, including CCL3 (i.e., macrophage inflammatory protein-1α (MIP-1α)) and CCL4 (MIP-1β), which are small peptides required for the recruitment of immune cells to the site of infection or inflammation." (PMID 36232381, 2022). "Furthermore, we could only identify a trend or correlation between levels of IL-1β expression and those of IL-6, CCL3 and CCL4 in the very early infection phase (3 h) and at high bacterial loads (MOI = 1:1000)." (PMID 33652921, 2021). "In vitro infection of human NK cells by A. fumigatus hyphae for 6 h increases the secretion of inflammatory cytokines, such as IFN-γ, TNF-α, and growth factor GM-CSF, as well as several chemokines, including CXCL8/IL-8, CCL3/MIP-1α, CCL4/MIP-1β, and XCL1/lymphotactin." (PMID 34575791, 2021). "Secretions of the chemokines CXCL1 and CCL3 were significantly higher in infected ECD mice compared to infected control mice one-week post infection (p < 0.0001), there was a decrease in the chemokine levels by 2 weeks post infection, which is like the trend observed for mice infected at ZT3." (PMID 32958779, 2020). "Instead, we observed chemokines as particularly affected by the presence of the parasite, since IL-8, CCL3, CCL4 and CCL5 were significantly reduced in concentration in Ss+ subjects compared to CTRL, suggesting that immune cell recruitment to the infection site might be dampened in these patients." (PMID 33059754, 2020). "Importantly, in these cases CCL3 is essential for protective mechanisms involving the recruitment of effector CD8+ T-cells and macrophages to the sites of infection, robust early production of cytokines (TNF and IFNγ), induction of cytolytic activity and generation of radical oxygen intermediates." (PMID 32194558, 2020). "However, another study performed using the hRSV Long strain showed that CXCL8 levels were not changed upon infection with hRSV, while CCL3 and CCL5 levels were increased." (PMID 30936869, 2019). "In this study we show, that NK cells secrete chemokines such as CCL3/MIP-1α, CCL4/MIP-1β and CCL5/RANTES early on after stimulation with Aspergillus fumigatus and, in addition, adjust the concentration of chemokines released to the multiplicity of infection of Aspergillus fumigatus." (PMID 30563459, 2018). "At this stage of infection, only CCL3 and CXCL9 showed no changes in mRNA expression." (PMID 27688600, 2016). "Therefore, levels of CXCR3 (receptor for CXCL9 and CXCL10), CXCR5 (receptor for CXCL13), CCR5 (receptor for CCL3 and CCL5), and CCR7 (receptor for CCL19) were analyzed on CD45hiCD11bloCD19+ B cells which infiltrated the brain at 7, 14, 30, and 60 days post infection." (PMID 27207308, 2016). "The levels of inflammatory cytokines and chemokines, i.e., IL-6, TNF-α, CCL3/MIP-1α, CXCL1/KC, and CXCL10/IP-10, which have been reported to contribute to lung pathology, also decreased in BALF from Mint3−/− mice compared to those from WT mice on day 4 after infection." (PMID 27883071, 2016). "To investigate whether the NLRP7 inflammasome plays a role in the production of TNF-α and CCL3 besides IL-1β and IL-18, we silenced NLRP7 or ASC in THP-1 macrophages prior to infection, which significantly attenuated M. bovis-induced upregulation of TNF-α, CCL3 and IL-1β at the mRNA level." (PMID 27043315, 2016). "Furthermore, of the cytokines whose secretion was elevated by 1,25D treatment after infection (CCL3, CCL4, CCL8, IL-8, and TNF-α), treatment did not induce their secretion from uninfected cells." (PMID 23762029, 2013). "While IL-17R KO animals predictably had significantly higher amounts of IL-17 in brain abscess homogenates, several other mediators were also elevated between 7 and 14 days after infection, including IL-1α, IL-1β, IL-6, CCL3 and CXCL1 (data not shown), as well as CXCL2 and CXCL9." (PMID 22704602, 2012).